SBK2 (SH3 domain binding kinase family member 2)
Synonyms: SgK069
Tractability: Small molecule: it belongs to a druggable protein family.
Gene: Protein-coding gene on chromosome 19 (55,528,609 to 55,537,143, reverse strand). Ensembl gene ENSG00000187550.
Gene Ontology:
Molecular function: ATP binding; protein kinase activity; protein serine kinase activity; protein serine/threonine kinase activity
Biological process: MAPK cascade
Genetic constraint (gnomAD): Loss-of-function variants: 18 observed, 14.66 expected, observed/expected ratio (o/e) 1.23, 90% interval 0.85 to 1.77. The synonymous counts are far from expectation, so gnomAD's model fits this gene poorly and the ratio says little. Missense variants: 581 observed, 420.68 expected, observed/expected ratio (o/e) 1.38, 90% interval 1.29 to 1.48. Synonymous variants: 284 observed, 195.99 expected, observed/expected ratio (o/e) 1.45, 90% interval 1.31 to 1.6.
Homologues: Orthologues: macaque SBK2 (95% identical), dog SBK2 (82% identical), mouse Sbk2 (82% identical), pig SBK2 (81% identical), rat Sbk2 (81% identical), guinea pig SBK2 (76% identical), chimpanzee SBK2 (66% identical), tropical clawed frog sbk2 (46% identical). Paralogues in human: STK10 (23% identical), TNIK (22% identical), MINK1 (22% identical), MAP4K1 (22% identical), MAP4K3 (21% identical), MAP3K19 (21% identical), MAP4K4 (21% identical), SLK (21% identical), MAP4K5 (21% identical), PAK4 (21% identical), MAP3K14 (20% identical), MAP4K2 (20% identical), and 23 more.
Diseases named in the same sentence as SBK2 in open-access papers:
SBK2 is named in the same sentence as 4 diseases in open-access papers, as found by Europe PMC text mining. Sharing a sentence is not in itself a finding about the gene and the disease. The quoted sentences say what the papers report.
glioma (1 paper, 2017). A benign or malignant brain and spinal cord tumor that arises from glial cells (astrocytes, oligodendrocytes, ependymal cells). "Fluorophores conjugated to the integrin-targeting peptide RGD (IRDye 800CW-RGD) or the protein tyrosine phosphatase mu-targeting peptide SBK2 (Cy5-SBK2) showed a TNR of 16.3–79.7 and 11.7–19.8, respectively, dependent on the glioma cell line being observed." (PMID 27878374, 2017).
tumor (2 papers, 2015 to 2017). "We have previously developed a molecular imaging agent that specifically binds to the PTPμ extracellular fragment, called SBK2 that is linked to a fluorophore, and labels both the main GBM tumor mass and greater than 99% of the dispersing cells up to 3.5 mm away from the main tumor." (PMID 26435847, 2015).
cancer (1 paper, 2020). A tumor composed of atypical neoplastic, often pleomorphic cells that invade other tissues. "Cox-proportional hazard ratios on Tdark kinases and their CNAs reveal that SBK2, ETNK2, PSKH2, SCYL3, and NRBP2 are all significantly prognostic for survival across all cancers." (PMID 33205077, 2020).
SBK2 also shares sentences with these, for which no sentence is quoted: glioblastoma (1 paper).